TCAF1 (TRPM8 channel associated factor 1)
Description:
Positively regulates the plasma membrane cation channel TRPM8 activity. Involved in the recruitment of TRPM8 to the cell surface. Promotes prostate cancer cell migration inhibition in a TRPM8-dependent manner.
Synonyms: FAM115A; KIAA0738; GATD9A
Tractability: Antibody: UniProt places it where antibodies can reach, with high confidence; its Gene Ontology location is reachable by antibodies, with high confidence. PROTAC: ubiquitination databases record sites on it.
Gene: Protein-coding gene on chromosome 7 (143,851,364 to 143,903,890, reverse strand). Ensembl gene ENSG00000198420.
Subcellular location: Cell membrane
Subcellular location (Human Protein Atlas): Cell Junctions; Nuclear bodies; Vesicles
Gene Ontology:
Molecular function: protein binding; transmembrane transporter binding
Biological process: negative regulation of cell migration; positive regulation of anion channel activity; positive regulation of protein targeting to membrane; regulation of monoatomic anion transmembrane transport
Cellular component: plasma membrane
Genetic constraint (gnomAD): Loss-of-function variants: 4 observed, 12.01 expected, observed/expected ratio (o/e) 0.33, 90% interval 0.16 to 0.76. The upper end of that interval is the gene's LOEUF score, 0.76, which puts it in group 3 of 6, group 1 being the genes least tolerant of losing a copy. Missense variants: 255 observed, 267.63 expected, observed/expected ratio (o/e) 0.95, 90% interval 0.86 to 1.06. Synonymous variants: 105 observed, 108.21 expected, observed/expected ratio (o/e) 0.97, 90% interval 0.83 to 1.14.
Homologues: Orthologues: chimpanzee TCAF1 (99% identical), macaque TCAF1 (99% identical), dog TCAF1 (98% identical), pig TCAF1 (96% identical), rabbit TCAF1 (96% identical), guinea pig TCAF1 (95% identical), rat Tcaf1 (90% identical), mouse Tcaf1 (90% identical), tropical clawed frog tcaf1 (41% identical), zebrafish zgc:162193 (38% identical), zebrafish si:ch211-210b2.4 (38% identical), zebrafish si:ch211-210b2.2 (37% identical), and 1 more. Paralogues in human: TCAF2 (65% identical), TCAF2C (49% identical).
Diseases named in the same sentence as TCAF1 in open-access papers:
TCAF1 is named in the same sentence as 6 diseases in open-access papers, as found by Europe PMC text mining. Sharing a sentence is not in itself a finding about the gene and the disease. The quoted sentences say what the papers report.
prostate carcinoma (4 papers, 2017 to 2024). A carcinoma that arises from epithelial cells of the prostate gland. "In prostate cancer, TCAF1 negatively regulates cell migration when bound to TRPM8, but TCAFs are partner proteins for other ion channels, including TRPV6." (PMID 36012311, 2022). "This is the first study to show a prognostic biomarker potential for RHCG and TCAF1 methylation in prostate cancer." (PMID 28052017, 2017). "This is the first study to demonstrate a significant prognostic value of RHCG and TCAF1 hypermethylation in prostate cancer." (PMID 28052017, 2017). "Several studies have reported that intragenic DNA methylation, as we observed for TCAF1 in prostate cancer, is involved in alternative TSS-regulation in normal and malignant tissue." (PMID 28052017, 2017). "Future studies should investigate TCAF1 methylation and potential isoform-specific expression patterns in NM and malignant prostate cells to elucidate its possible role in prostate cancer tumorigenesis and progression." (PMID 28052017, 2017). "In addition, the authors have found that TRPM8 and TCAF1 are upregulated in primary prostate cancer samples and downregulated in metastatic samples." (PMID 38816425, 2024). "Moreover, an important future task will be to investigate whether methylation of RHCG and TCAF1 can also predict prostate cancer aggressiveness at the time of diagnosis based on analysis of DNBs or even liquid biopsies, in order to guide treatment decisions." (PMID 28052017, 2017). "TCAF2 promotes cell migration in prostate cancer by recruiting TRPM8 to the cell membrane, whereas TCAF1 reduces the speed and migration of these cells." (PMID 36012311, 2022). "Here, using two large prostate cancer patient cohorts, we identified and independently validated RHCG, TCAF1, and the 2-gene panel RHCG-TCAF1 as novel independent adverse predictors of BCR after RP." (PMID 28052017, 2017). "TCAF1 was not significantly deregulated in the large TCGA dataset, yet we observed a modest but significant upregulation of this transcript in prostate cancer in the small dataset." (PMID 28052017, 2017). "Notably, aberrant hypermethylation of TCAF1 was specific to an intragenic CGI/shore region overlapping a putative alternative transcription start site (TSS), suggesting that hypermethylation of this region may stimulate transcription from the upstream TSS (TSS1) in at least some prostate cancers." (PMID 28052017, 2017).
pancreatic adenocarcinoma (1 paper, 2023). "In pancreatic adenocarcinoma, TRPM8 channels are associated with TRPM8 channel-associated factors 1 and 2 (TCAF1 and TCAF2)." (PMID 37033630, 2023).
pancreatic cancer (1 paper, 2022). "First, we queried GEPIA to explore the relationship between the TRPV6, TRPA1, TRPM8, TCAF1, and TCAF2 mRNA expressions and sub-stages in pancreatic cancer samples, compared to the control (normal subjects)." (PMID 36012311, 2022). "First, using the GEPIA web platform as a bioinformatic tool, we explored the transcriptional levels of TRPV6, TRPA1, TRPM8, TCAF1, and TCAF2 in pancreatic cancer (n = 179) and normal pancreatic tissues (n = 171)." (PMID 36012311, 2022). "Consistent with the GEPIA results, the expression levels of TRPA1, TRPM8, TCAF1, and TCAF2 were significantly higher in pancreatic cancer tissue (p < 0.001), and TRPV6 expression was significantly lower in pancreatic cancer tissue compared to normal tissues (p < 0.001)." (PMID 36012311, 2022). "Next, we used UCSC Xena to explore the expression levels of TRPV6, TRPA1, TCAF1, TCAF2, and TRPM8 in pancreatic cancer (n = 178) and in normal pancreatic tissue (n = 167)." (PMID 36012311, 2022).
cancer (3 papers, 2017 to 2024). A tumor composed of atypical neoplastic, often pleomorphic cells that invade other tissues. "By suppressing mutations and genomic instability in normal cells, TCAF1 may serve to suppress cancer initiation." (PMID 38816425, 2024). "From this list, 8 novel top candidate genes were selected based on their display of highly cancer-specific hypermethylation over multiple adjacent promoter-associated DMCs: COL4A6, CYBA, HLF, LINC0134 (LOC149234), LRRC4, PROM1, RHCG, and TCAF1 (FAM115A)." (PMID 28052017, 2017). "However, by protecting the genome of cancer cells and promoting their survival in the presence of replication stress, TCAF1 may promote cancer progression." (PMID 38816425, 2024). "Thus, TCAF1 may be targeted for treating cancers with intrinsic or induced replication stress." (PMID 38816425, 2024). "The identification of TCAF1 as a novel genome protection factor and TRPV2 regulator broadens our understanding of its molecular functions and sheds new light on its cancer relevance." (PMID 38816425, 2024). "The results showed that TCAF1 and TCAF2 are expressed in cancer tissues and are located at the cytoplasmic and membrane levels." (PMID 36012311, 2022).
tumor (3 papers, 2016 to 2022). "We found significantly higher expression levels of TRPA1, TRPM8, and TCAF1/F2 in tumoral tissues compared to normal tissues, but lower expression levels of TRPV6, suggesting that TRP channels have either tumor-suppressive or oncogenic roles." (PMID 36012311, 2022). "In particular, TCAF-1 is more expressed in the early tumor stages favoring cancer development, while its expression as well as that of TRPM8 is reduced during the tumor spreading with metastasis." (PMID 27289382, 2016). "TCAF1 and TCAF2 did not correlate with tumor stage or lymph node invasion (data not shown)." (PMID 36012311, 2022). "Experimental design: Eight novel candidate markers, COL4A6, CYBA, TCAF1 (FAM115A), HLF, LINC01341 (LOC149134), LRRC4, PROM1, and RHCG, were selected from Illumina Infinium HumanMethylation450 BeadChip analysis of 21 tumor (T) and 21 non-malignant (NM) prostate specimens." (PMID 28052017, 2017).
TCAF1 also shares sentences with these, for which no sentence is quoted: cervical carcinoma (1 paper).